DGCR8 (DGCR8 microprocessor complex subunit)
Diseases named in the same sentence as DGCR8 in open-access papers (continued):
Sharing a sentence is not in itself a finding about the gene and the disease.
tumor (45 papers, 2007 to 2025). "The DGCR8-mutated cases and subsets of cases with low DGCR8 expression translate into a specific miRNA profile, correlating with dedifferentiation and tumour progression." (PMID 41104964, 2025). "In the past two years, research has discovered that germline pathogenic variants (GPVs) in DGCR8 are associated with tumor predisposition, and that GPVs in AGO1/2 are linked to neurodevelopmental disorders (NDDs)." (PMID 39457367, 2024). "At germline level, these genes are known to cause at least three distinct genetic syndromes, with clinical manifestations that range from tumor predisposition (DGCR8 and DICER1 germline mutations) to neurodevelopmental disorders (AGO1/2 germline mutations)." (PMID 38607000, 2024). "As the loss of the WT allele is suggested for tumorigenesis, DGCR8 seems to act as a tumor-suppressor gene for which the E518K allele confers transforming properties." (PMID 38607000, 2024). "While AGO1 and DGCR8 mutations conferred around 2.5 times higher risk of advanced tumor size, DROSHA mutations were 2.5 times more likely to present with poorly differentiated tumors at the time of diagnosis." (PMID 36672288, 2023). "Thus, our data reveal that K707 -SUMOylation of DGCR8 is linked to its new functions in regulation of tumorigenesis and tumor cell migration." (PMID 26202964, 2015). "SUMO1-conjugation at DGCR8 K259 prevents DGCR8 from nuclear export and confers tumor suppression function." (PMID 41403701, 2025). "In this section, we report its observed frequency in DICER1- and DGCR8-altered tumours strictly as an observational correlate." (PMID 41104964, 2025). "The E518K mutation causes a reduction of critical miRNAs in tumors, which is consistent with the observation that the knockdown of DGCR8 promotes tumor growth." (PMID 38607000, 2024). "Both DICER1 and DGCR8 are postulated to exhibit tumor-suppressive functions, which is supported by the biallelic inactivation pattern observed in syndromic and sporadic cases." (PMID 38252873, 2024). "Larger tumor size was associated with both AGO1 (OR = 2.54, 1.25–5.18, p = 0.010) and DGCR8 (OR = 2.75, 1.47–5.17, p = 0.002) mutations." (PMID 36672288, 2023). "The strong correlation between the mRNA level of PUS10 and that of established microRNA biogenesis-associated proteins, such as DICER, DGCR8, AGO1 and AGO3, in KIRC tumor tissues hinted at the involvement of PUS10 in microRNA processing." (PMID 37596681, 2023). "This mutation disrupts global miRNA production and DGCR8-mutated tumours display a specific miRNA profile different from DGCR8-WT tumours." (PMID 36499151, 2022). "Somatic loss of chromosome 22, containing the wild-type (WT) allele, appears to be required for tumorigenesis, indicating that DGCR8 acts as a tumour suppressor gene." (PMID 36499151, 2022). "In metastatic HCC, METTL14 interacts with the microprocessor protein DiGeorge syndrome critical region 8 (DGCR8) to suppress tumor metastasis." (PMID 35974338, 2022). "Here, we find that the microRNA biogenesis factor DGCR8 promotes tumor resistance to X-ray radiation independently of its Drosha-binding ability." (PMID 34188037, 2021). "Two recent studies have shown that m6A modification can influence tumor progression by affecting the binding of DGCR8 to pri-miRNAs." (PMID 34490238, 2021). "WBP2 protein blocks the microRNA biogenesis via physical interactions with the microprocessor complex, and reverts the tumor-suppressive role of DGCR8." (PMID 34117091, 2021). "2D and 3D in vitro proliferation assays revealed that WBP2 blocked the tumor-suppressive properties of DGCR8, a key component of the microprocessor complex." (PMID 34117091, 2021). "Through the detection of HNSCC tumor tissue and the analysis of TCGA database, we found that DGCR8, a protein that affected the maturation of miRNA, promoted the transcription of hsa-miR-106a and had a strong correlation." (PMID 33385002, 2020).
tumor (continued). "K707-SUMOylation of DGCR8 increases its affinity with pri-miRNAs and directs the function of pri-miRNAs in oncogenic gene silencing, which promotes tumorigenesis and tumor cell migration." (PMID 29020972, 2017). "Sufficient DNA was available on 16/19 MLLT1-mutant tumours to perform mutation analysis for WT1, CTNNB1, WTX, DROSHA, DGCR8, and SIX1/2 and this revealed five CTNNB1 mutations, one WTX mutation, and no WT1 DROSHA, DGCR8, or SIX1/2 mutations." (PMID 26635203, 2015). "We found that the SUMO-site mutation of DGCR8-K707R inhibited the anchor-independent growth, xenograft tumor growth and tumor cell migration, and SUMOylation of DGCR8 enhanced its affinity with pri-miRNA as well as the direct repression of target by pri-miRNA." (PMID 26202964, 2015). "This reduction is consistent with findings that silencing DGCR8 promotes tumor growth." (PMID 39457367, 2024). "In 28 cases, the DGCR8 gene expression between the tumour and its respective NTAT was available." (PMID 36499151, 2022). "For instance, methyltransferase-like (METTL)-3 might act as an oncogene by interacting with the DiGeorge syndrome critical region 8 (DGCR8) and accelerating the pri-miR221/222 maturation to promote tumor proliferation." (PMID 35148766, 2022). "Moreover, the tumor specimens were all stained by immunohistochemistry to show the expression of DGCR8, SPI1, TNF-α, nestin, and Ki-67." (PMID 35945192, 2022). "Finally, our work calls for the development of small-molecule inhibitors that target USP51’s DUB activity or its interaction with DGCR8; such inhibitors have potential as tumor radiosensitizers." (PMID 34188037, 2021). "To determine whether DGCR8 is upregulated in radioresistant tumor cells, we used X-ray IR to select radioresistant subpopulations from LM2 and MCF-7 cell lines." (PMID 34188037, 2021). "Moreover, we demonstrate that gemcitabine chemoresistance was a result of decreased expression of Drosha and DGCR8 in AsPC‐1 cells and tumor cell‐engrafted models." (PMID 30341811, 2018). "Among them, p63, an essential transcription factor for epidermal function and an antiaging molecule, directly promotes the transcription of DGCR8 and Dicer; ING proteins (inhibitor of growth), a family of tumor suppressors and senescence promoters, repress DGCR8 expression." (PMID 28593022, 2017). "Moreover, tumor growth of A549luc group transfected with DGCR8-K707R was almost completely inhibited whereas the DGCR8-WT group grew normally." (PMID 26202964, 2015). "In addition, the rs3742330 of DICER1, rs784567 of TARBP2, rs417309 of DGCR8, and rs14035 of RAN as well as rs11077 of XPO5 are associated with the LC progression depending on the tumor size." (PMID 26688807, 2015). "Moreover, SUMOylation at K707 of DGCR8 was involved in the regulation of tumorigenesis and tumor cell migration, which was probably contributed to its influencing on the formation of pri-miRNA /target mRNA complex." (PMID 26202964, 2015). "To test whether SUMOylation of DGCR8 influences the migration ability of tumor cell as well, we evaluated the cell motility by RTCA." (PMID 26202964, 2015). "Additionally, rs417309 of DGCR8, rs3742330 and rs13078 of DICER1, and rs784567 of TARBP2 as well as rs11077 of XPO5 are associated with the progression of LC depending on the tumor size and lymph node metastases." (PMID 26688807, 2015). "This strongly supports our hypothesis that the mutational status of DICER1 and DGCR8 rather than tumor histotype determines the global change in miRNA expression." (PMID 38252873, 2024). "The findings of miRNA dysregulation in DICER1 and DGCR8 mutants were consistently supported by the results obtained by analyzing TCGA data from PTCs, suggesting that the mutational effect on miRNA profiles is apparent irrespective of tumor type." (PMID 38252873, 2024).
tumor (continued). "It was advanced the DGCR8 p.(E518K) mutation could influence the tumour progression or invasive behaviour without driving the tumour per se, since the tumours with this mutation are always described to bear additional genetic events." (PMID 36499151, 2022). "However, K259-SUMOylation of DGCR8 promoted by the tumor suppressor p14ARF mainly maintains its nuclear localization to function as a partner of Drosha in the MC complex, which prevents the aberrant miRNA biogenesis and exerts its tumor-suppressive function." (PMID 29020972, 2017). "SUMOylation of DGCR8 did not alter its association with Drosha, or miRNA biogenesis, but rather affected the affinity with pri-miRNAs to control the direct function of pri-miRNAs in target repression, which was linked to tumorigenesis and tumor cell migration." (PMID 26202964, 2015). "Furthermore, the DGCR8 rs1640299, DICER1 rs3742330 and rs13078, RAN rs14035, and XPO5 rs11077 as well as rs784567 of TARBP2 genes single nucleotide polymorphisms have demonstrated an association with tumor progression depending on the lymph node metastases." (PMID 26688807, 2015). "By regulating the microprocessor protein DGCR8, METTL14 promotes the maturation of PRI-mir126 into mature mir126, a tumor suppressor of HCC metastasis." (PMID 36147735, 2022). "Meta-analyses suggest that microprocessor complex components, in particular DGCR8, DDX5, and DEAD-Box Helicase17 (DDX17), have tumor-suppressive properties." (PMID 34117091, 2021). "We transfected codon-optimized LT (LTco), tumor-derived truncated LT (LT339), and codon-optimized sT (sTco) into MCPyV− MCC cell lines and evaluated the effect on expression levels of DROSHA, DGCR8, DICER1, and TARBP2 using western blotting." (PMID 34761184, 2021). "Further studies have found that LINC01234 can interact with HNRNPA2B1, which in turn leads to the recruitment of DiGeorge syndrome critical region gene 8 (DGCR8), promoting cell proliferation in vitro and tumor growth in vivo." (PMID 33552994, 2020). "We observed significant over-expression of ADAR, ADARB1, DDX5/17/20, DGCR8, DICER1, DROSHA, EIF2C1-4 (AGO1-4), GEMIN4, POLR2A, TARBP2, TNRC6A and XPO5 in tumor tissue compared to adjacent mucosa." (PMID 31510013, 2019). "Knockdown of DGCR8, as well as restoration of DGCR8 expression, had no substantial effect on tumor growth without irradiation." (PMID 34188037, 2021). "In addition, the expression of DDX5/20, DGCR8, DICER1, DROSHA, EIF2C1-4, GEMIN4, TNRC6A and XPO5 was deregulated not only in tumor tissue, but also in corresponding liver metastases compared to adjacent tissue." (PMID 31510013, 2019). "Two tumours with MLLT1 mutations also had CTNNB1 mutations; no MLLT1-mutant tumours had accompanying WT1, WTX, DROSHA, DGCR8, SIX1, or SIX2 mutations." (PMID 26635203, 2015). "Unfortunately, DGCR8 and AGO2 mRNA expression levels were not statistically associated with age, tumor stage (TNM), CEA titer, and BMI clinical parameters in our CRC specimens." (PMID 23775303, 2014). "As we found many changes in miRNA expression across the five clinical tumor subtypes we had defined above, we asked whether DICER1, DROSHA, DGCR8, AGO1, AGO2, AGO3 or AGO4 expression differs among these subgroups." (PMID 17922911, 2007). "Aberrant expression of miRNA biosynthesis genes DGCR8 and DROSHA are described to promote tumorigenesis as it results in aberrant miRNA expressional pattern that could be at play even at the level of tumour initiation, by downregulating tumour suppressor genes or overexpressing oncogenes." (PMID 36499151, 2022). "Hence, the tumor-suppressive role of DGCR8 might also not be necessary as a result of its miRNA-processing role." (PMID 34117091, 2021). "In this study, we uncovered a non-canonical function of DGCR8 in DSB repair signaling and tumor radioresistance." (PMID 34188037, 2021).
tumor (continued). "Altogether, these findings reveal the non-canonical function of DGCR8 in DSB repair and suggest that radiation treatment may result in therapy-induced tumor radioresistance through ATM- and USP51-mediated activation and upregulation of DGCR8." (PMID 34188037, 2021). "Furthermore, key regulators of the miRNA pathway, including DROSHA, DGCR8, AGO1 and AGO2 are frequently overexpressed—rather than downregulated—in HCC, and specifically AGO2 overexpression has been shown to promote HCC progression, tumor vascularization and metastasis." (PMID 31732746, 2019).
psychiatric disorder (6 papers, 2014 to 2021). A disorder characterized by behavioral and/or psychological abnormalities, often accompanied by physical symptoms. "Several genes encoded in the 1.5-Mb region (e.g., Tbx1, Dgcr8, Comt, Sept5, and Prodh) have been identified as potentially associated with psychiatric disorder-like behavioral phenotypes." (PMID 33845872, 2021). "In fact, some genes within the 1.5-Mb region (e.g., Tbx1, Dgcr8, Prodh, and Sept5) have been identified as potentially associated with phenotypes relevant to psychiatric disorders by animal model studies." (PMID 32066675, 2020). "In our view, this Dgcr8–Drd2 mechanism at thalamo-LA projections may underlie some pathogenic mechanisms related to emotional memory disturbances in 22q11DS and associated cases of psychiatric disease." (PMID 28538174, 2017). "Our findings confirm previous reports and further suggest that haploinsufficiency of DGCR8 could alter the miRNA expression landscape and contribute to the wide clinical phenotype, including cognitive, neurocognitive, psychiatric disorders and cardiac disease, observed in 22q11DS." (PMID 25084529, 2014).
infection (5 papers, 2014 to 2024). The state of being infected such as from the introduction of a foreign agent such as serum, vaccine, antigenic substance or organism. "The mRNA levels of Dicer, Drosha, and DGCR8 were all significantly downregulated following the infection, bottoming out at 3 days post-infection and coinciding with an increase in viral replication." (PMID 31214179, 2019). "In order to characterise the role of miRNAs during EV71 pathogenesis, DGCR8 was knocked down prior to infection." (PMID 25047717, 2014). "Infection with flaviviruses, including Dengue virus and Kunjin virus, has been previously shown to result in the inhibition of RNAi machinery and a downregulation of Drosha and DGCR8." (PMID 27872619, 2016). "On the other hand, infection of Vero E6 cells with SARS-CoV-2 impacted mRNA levels of AGO2, DICER1, DGCR8, and XPO5 at 24 h." (PMID 37243263, 2023). "In another study, infection of A549 cells with dengue virus 4 resulted in reduced mRNA levels of DICER, DROSHA, and DGCR8." (PMID 37243263, 2023). "A significant increase in mRNA levels of AGO2, DICER1, DGCR8, and XPO (all p-values= 0.03) was found 24 h after infection." (PMID 37243263, 2023). "mRNA level changes of DICER1, DGCR8, and XPO were approximately 2-fold, and of AGO2 approximately 4.6-fold, 24 h after infection." (PMID 37243263, 2023). "The three cell types were infected with the SARS-CoV-2 delta variant at an MOI of 0.1, and mRNA expression levels of AGO2, DICER1, DGCR8, DROSHA, and XPO5 were measured 24 h and 48 h after infection." (PMID 37243263, 2023). "As a result of DGCR8 knockdown, EV71 is unable to regulate host miRNAs to enhance cellular microenvironment leading to the inability to establish infection." (PMID 25047717, 2014). "However, in Vero E6 cells, AGO2, DICER1, DGCR8, and XPO5 mRNA levels were slightly upregulated 24 h after infection with SARS-CoV-2." (PMID 37243263, 2023). "Another example is that infection with Kaposi’s sarcoma-associated herpesvirus (KSHV) resulted in increased expression of DICER1 mRNA in primary human umbilical vein endothelial cells, whereas mRNA expression levels of DGCR8, DROSHA, and XPO5 did not change significantly." (PMID 37243263, 2023). "The results showed that infection of NHBE and Calu-3 cells with SARS-CoV-2 did not impact mRNA expression levels of AGO2, DICER1, DGCR8, DROSHA, and XPO5 at 24 and 48 h post infection, in good concordance with our results on patient samples." (PMID 37243263, 2023).
cardiac disease (2 papers, 2014 to 2019). "Our study highlighted DGCR8 as a potential therapeutic target for heart diseases related to early exposure to dietary challenge." (PMID 30854230, 2019).
hematologic malignancies (1 paper, 2025). "Looking forward, miRNA-based therapies targeting upstream steps of miRNA processing—such as Dicer and DGCR8—may offer novel therapeutic approaches for hematologic malignancies characterized by impaired miRNA biogenesis." (PMID 41463093, 2025).
immune disorders (1 paper, 2025). "Loss of DROSHA or DGCR8 disrupts miRNA production and impairs regulatory T cells homeostasis and thus is suggested to drive immune disorders." (PMID 41403701, 2025).
neurodevelopmental disorder (1 paper, 2020). A behavioral and cognitive disorder with onset during the developmental period that involves impaired or aberrant development of intellectual, motor, or social functions. "DGCR8 abnormal expression may thus constitute a nonspecific risk factor for neurodevelopmental disorders." (PMID 33149139, 2020).
neurological disease (1 paper, 2025). "In one individual, the deletions spared both TBX1 and DGCR8, whose haploinsufficiency has been linked, respectively, with cardiac and neurological disease manifestations." (PMID 41368632, 2025).
DGCR8 also shares sentences with these, for which no sentence is quoted: autism (3 papers); Intellectual disability (2); Kidney Cyst (2); psychosis (2); acute coronary syndrome (1); atherosclerosis (1); Azoospermia (1); benign tumours (1); childhood cancers (1); clear cell renal cell carcinoma (1); colorectal adenocarcinoma (1); DICER1 syndrome (1); esophageal cancer (1); fibrosis (1); follicular thyroid carcinoma (1); genetic disorder (1); heart abnormalities (1); Huntington disease (1); Hyperglycemia (1); hypertrophy (1); lung adenoma (1); migraine (1); motor neuron diseases (1); mucosal (1); myocardial infarction (1); neurodegenerative disease (1); Obesity (1); oligospermia (1); oral squamous cell carcinoma (1); Papillary Thyroid Carcinoma (1).
A further 10 diseases each share a sentence with DGCR8 in 1 paper.